IL15 (interleukin 15)
Diseases named in the same sentence as IL15 in open-access papers (continued):
Sharing a sentence is not in itself a finding about the gene and the disease.
celiac disease (56 papers, 2008 to 2025). An autoimmune genetic disorder with an unknown pattern of inheritance that primarily affects the digestive tract. "Celiac disease is associated with chronic intestinal inflammation, leading to the overexpression of IL-15 and proliferation of intraepithelial lymphocytes." (PMID 40981003, 2025). "Gliadin peptides, in celiac disease patients, can also cause the secretion of interleukin-15 (IL-15) from enterocytes and dendritic cells." (PMID 38396767, 2024). "The chronic up-regulation of IL-15 in the intestinal mucosa was a hallmark of celiac disease and it was related to the degree of mucosal damage." (PMID 36613665, 2022). "Upregulation of IL-15 in both the epithelium and the lamina propria is a hallmark of coeliac disease and correlates with the degree of mucosal damage seen in these patients." (PMID 35450067, 2022). "Though dysregulated expression of IL-15 has been implicated in many inflammatory autoimmune diseases, it is considered to be the hallmark of celiac disease due to chronic upregulation in the intestinal epithelium and lamina propria." (PMID 33435615, 2021). "The innate immune response is associated with the production of pro-inflammatory cytokines associated with mucosal damage and celiac disease “hallmark” IL-15." (PMID 33435615, 2021). "Overexpression of interleukin-15 (IL-15) is linked with immunopathology of several autoimmune disorders including celiac disease." (PMID 30050538, 2018). "For instance, earlier studies have suggested that IL-15 and retinoic acid are highly pathogenic factors in celiac disease, since they induce production of IL-12 by intestinal DCs." (PMID 24982658, 2014). "Intestinal IL-15 has been implicated in promoting gut dysbiosis in mice and humans and may be involved in predisposing individuals to celiac disease." (PMID 36463221, 2022). "Another hallmark of celiac disease is NF‐κB‐regulated IL‐15 expression." (PMID 34125490, 2021). "Interleukin-15 (IL-15), secreted from the intestinal epithelium and antigen-presenting cells in response to gliadin peptides, plays an important role in the underlying innate immune response in the intestinal mucosa of patients with celiac disease." (PMID 25705619, 2014). "By contrast, in celiac disease, the expression of IL-15 activates cytotoxic T cells and damage epithelial cells." (PMID 40319445, 2025). "Several studies have indicated that IL-15 contributes to the progression of autoimmune disorders like RA, inflammatory bowel disease, and coeliac disease." (PMID 40957221, 2025). "IL-15 levels correlate positively with active lesions in patients with celiac disease (CeD), highlighting its importance in CeD." (PMID 39104791, 2024). "For example, dysregulated IL-15 expression in celiac disease resulted in NKG2D-dependent CD8 T cell killing of target cells and promoted immunopathological responses." (PMID 37603573, 2023). "CALY-002 is a humanized monoclonal antibody inhibiting interleukin-15 (IL-15), which is being assessed in celiac disease and EoE in a phase 1 RCT (NCT04593251)." (PMID 37894846, 2023). "In the GI tract, IL-15 is overexpressed in the gut mucosa of patients with celiac disease and is thought to contribute to epithelial damage." (PMID 36830973, 2023). "The efficacy of TM-β1 (the anti-mouse IL-2Rβ equivalent of Hu-Mik-β1) was evaluated in a mouse model of celiac disease using transgenic mice that express IL-15 in intestinal cells using an enterocyte-specific T3b promoter to drive the transgene." (PMID 35592318, 2022). "In coeliac disease, selenium has been recommended as a therapeutic measure to block IL-15, in turn decreasing epithelial damage and preventing extra-intestinal complications." (PMID 35450067, 2022). "The expression of IL-15 in the intestines, as another characteristic indicator for identifying celiac disease, played a crucial role in the potential innate immune response of intestinal mucosa in celiac patients." (PMID 35681310, 2022).
celiac disease (continued). "The anti-IL-15 Ab from Amgen AMG-714 or HuMax-IL15 has shown efficacy in a xenograft model of human psoriasis, RA, and coeliac disease." (PMID 35592318, 2022). "These IELs contribute to villous atrophy and overall mucosal damage observed in active celiac disease by killing intestinal epithelial cells (IECs) producing stress signals, including IL-15." (PMID 33435615, 2021). "The primary role of IL-15 in celiac disease pathogenesis is to signal for lymphocytes to infiltrate the submucosa." (PMID 33435615, 2021). "IL-15 is essential both for maintaining IEL homeostasis and inducing IEL responses to epithelial stress, which has been associated with Coeliac disease." (PMID 34257288, 2021). "By contrast in celiac disease, IL-15 sustains intestinal inflammation, inhibiting TGF-β-mediated immunosuppressive signaling in human T lymphocytes." (PMID 31360169, 2019). "Our group previously reported IL-15 small intestinal overexpression as well as IL-17/22 dis-regulation and MHC II genetic predisposition in rhesus macaques with celiac disease characteristics." (PMID 30050538, 2018). "A model that recapitulates selected features of celiac disease, by utilizing transgenic mice overexpressing human IL-15 in the intestinal epithelium has been employed to investigate the role of IL-15 in disease pathogenesis." (PMID 30050538, 2018). "Here, we utilized an anti-human IL-15 antibody 04H04 (anti-IL-15) to reverse immunopathogenesis of celiac disease." (PMID 30050538, 2018). "An anti-IL-15 antibody, which like 04H04 inhibits IL-15 receptor signaling, has been clinically tested in celiac disease patients (NCT02633020, NCT02637141)." (PMID 30050538, 2018). "Due to the effector role CD8+ and CD4+ T cells play in pathogenesis of celiac disease, the impact of anti-IL-15 treatment on small intestinal CD3+CD4−CD8+CD45+ and CD3+CD4+CD8−/+CD45+ T cells secreting IFN-γ was evaluated." (PMID 30050538, 2018). "The overexpression of IL-15 in the small intestine of a gluten-sensitive patient is considered one of the key hallmarks of celiac disease." (PMID 30050538, 2018). "Due to close similarities in pathogenesis and immunology with human celiac disease, the rhesus macaque model was used to evaluate the efficacy of anti-IL-15 treatment in this study." (PMID 30050538, 2018). "An IL-15 overexpression has been reported in several pathological gut conditions, such as celiac disease and chronic inflammatory disorders." (PMID 28797042, 2017). "Overall, with the exception of IL-15, a pro-inflammatory cytokine considered to be a central factor in the pathogenesis of celiac disease, cytokine levels appeared to decrease with respect to increasing symptom severity." (PMID 29214007, 2017). "Upon IEC damage, IL-15 production increases, as observed during celiac disease, and correlates strongly with IEL activity." (PMID 29075263, 2017). "Several studies have reported that enterocytes are an important intestinal source of inflammatory IL-15, both in healthy and in food related disorders, as celiac disease." (PMID 28797042, 2017). "Research has shown that IL-15 expression plays a role in mediating intestinal inflammation in models of celiac disease and Crohn's disease, suggesting a possible link between IL-15, gut microbiota, and intestinal inflammation." (PMID 25517731, 2014). "IL-15 also prevents apoptosis of the cytotoxic intraepithelial lymphocytes that plays a central role in the refractory celiac disease via the JAK 3/STAT 5 signaling pathway." (PMID 25705619, 2014). "This ligand receptor interaction is enhanced by IL-15, leading to stimulation and proliferation of cytotoxic T lymphocytes that induce epithelial apoptosis and also results in development of refractory celiac disease and its malignant transformation." (PMID 25705619, 2014). "IL-15 is considered to be the major factor responsible for the immunopathogenesis of celiac disease, and for this reason it has been considered as a possible therapeutic target." (PMID 23533306, 2013).
celiac disease (continued). "IL-15 plays a major role in the development of the inflammatory immune response, and the upregulation of IL-15 is involved in the development of several autoimmune and chronic inflammatory disorders, such as RA, psoriasis and celiac disease." (PMID 24391825, 2013). "As a physiological example of this scenario is represented by the expression of NCRs on IEL in celiac disease, an autoimmune disorder where the cytokine IL-15 can drive a pathologic expansion of TCR-αβ IELs with an NK cell-like phenotype." (PMID 23518691, 2013). "In active celiac disease, IL-15 is considered a crucial cytokine in maintaining autoimmune (Th1/Th17) pathology, a relationship now recognized somewhat incongruously as being dependent on retinoic acid." (PMID 22346753, 2012). "In celiac disease (CeD), interleukin 15 (IL-15) affects the epithelial barrier by acting on intraepithelial lymphocytes, promoting interferon γ (IFN-γ) production and inducing strong cytotoxic activity as well as eliciting apoptotic death of enterocytes by the Fas/Fas ligand system." (PMID 39937025, 2025). "IL-15 is elevated in conditions like inflammatory bowel disease and celiac disease." (PMID 37836457, 2023). "However, in cases of inflammatory bowel disease and celiac disease, IL-15 production is increased, leading to the recruitment and activation of inflammatory and innate immune cells and the production of IFN-γ and TNF-α." (PMID 38140264, 2023). "A phase I/II clinical trial involving BNZ-1-targeted T-cell malignancies CTCL and LGLL has been completed (NCT03239392), and the efficacy of BNZ-1 and BNZ-2 (IL-15/21) is currently being evaluated in alopecia areata and refractory coeliac disease, respectively." (PMID 35592318, 2022). "Moreover, the expression of IL15 in the mucosa of patients with CD and UC as in celiac disease has been reported to be higher as compared to controls." (PMID 36439157, 2022). "A study with intestinal biopsy cultures obtained from celiac disease patients showed that regulatory T cells exist in the mucosa of untreated celiac disease patients, but they are dysfunctional due to the overexpression of IL-15 derived from epithelial cells." (PMID 32349426, 2020). "Indeed, epithelial cells such as enterocytes and hepatocytes have been suggested as the main source of IL-15 in the case of celiac disease and AHA, respectively." (PMID 31827070, 2019). "Moreover, in celiac disease, NKG2DhighCD8+ T cells induced by IL15 displayed cytotoxicity against intestinal epithelial cells expressing high MIC levels in a TCR-independent and NKG2D-mediated cytolysis pathway." (PMID 30333822, 2018). "Therefore, to examine the involvement of IL-15 in a model that is more representative of human celiac disease, we used the primate (rhesus macaque) model of GSE." (PMID 30050538, 2018). "Overall, providing the beneficial disease-modulatory and immunomodulatory effects observed, anti-IL-15 treatment might be considered as a novel therapy to normalize intestinal lymphocyte function in celiac disease patients with GSE." (PMID 30050538, 2018). "Thus, anti-IL-15 antibody has potential for the treatment of celiac disease and other inflammatory diseases in which IL-15 is involved." (PMID 30050538, 2018). "IL-15 induces the secretion of IL-21 by IELs, observed in celiac disease, which may be part of a self-sustaining feed-forward loop as observed in Th17 cells, enhancing IEL activation and cytotoxicity." (PMID 29075263, 2017). "Interestingly, a similar experimental approach has been used to assess the pro-inflammatory effect of IL-15 in coeliac disease, that suggested the promising use of molecules blocking IL-15 to rescue gut immune homeostasis." (PMID 28797042, 2017). "Upon our analyses, Gata4 deleted mice did not display classical signs of celiac disease associated signature, such as for instance, modification in the expression of IL-15 or activating natural killer receptor NKG2D gene transcripts (data not shown)." (PMID 27827449, 2016).
celiac disease (continued). "Increased expression of IL-15 has been reported in celiac disease and inflammatory bowel disease, which is critical in disease pathogenesis to induce proinflammatory cytokines, initiate epithelial apoptosis and trigger an anti-apoptotic pathway in human intraepithelial lymphocytes." (PMID 26600079, 2015). "Anti-IL-15 human monoclonal antibody has been evaluated in patients with other autoimmune disease such as rheumatoid arthritis, but despite the promising findings, a human study for celiac disease is still awaited." (PMID 25705619, 2014). "Damage to intestinal mucosa in celiac disease (CD) is mediated both by inflammation due to adaptive and innate immune responses, with IL-15 as a major mediator of the innate immune response, and by proliferation of crypt enterocytes as an early alteration of CD mucosa causing crypts hyperplasia." (PMID 21364874, 2011). "Celiac sprue is widely regarded as a T cell–mediated inflammatory disease, but the discovery of an IL-15-mediated innate response to gluten calls into question whether adaptive immunity alone can cause disease." (PMID 18425213, 2008). "To assess if mNPs could also modify the immune system response, we evaluated the mRNA levels of the most representative cytokines involved in the development of the celiac disease lesions: IFNɣ for the adaptive immune system and IL-15 and IL-8 for the innate immunity." (PMID 34198897, 2021). "Intriguingly, the increased production of IL-15 by intestinal epithelial cells was observed only in coeliac disease patients with HLA-DQ allotypes, not only disturbing the integrity of the epithelial barrier to induce coeliac disease pathogenesis, but also altering the intestinal immune regulation." (PMID 32651763, 2020). "Our study is the first to describe that anti-IL-15 therapy is beneficial in preventing severe GSE including compromised epithelial integrity, inflammation and loss of small intestinal tissue architecture in a clinically relevant rhesus macaque model of celiac disease." (PMID 30050538, 2018). "IL-15 can inhibit regulatory CD4+ T (Treg) cells, increase the number of IELs with a cytotoxic phenotype in celiac disease patients, and is also required for the development of villous atrophy." (PMID 38396767, 2024). "In agreement with our findings, IL-15 enhances the cytotoxicity of NKG2D+ CD8 T cells in other diseases, such as alopecia, celiac disease, and acute hepatitis A infection." (PMID 37603573, 2023). "IL-15 has been reported to be upregulated in the inflamed tissue from patients with inflammatory bowel disease (IBD) and celiac disease." (PMID 32457246, 2020). "There is a consensus that IL-15, via promotion of intestinal NK and NKT cells, contributes to celiac disease pathogenesis, namely GSE." (PMID 30050538, 2018). "In light of the fact that one ILC1 subset is responsive to IL-12, while the other promptly reacts to IL-15, it would be interesting to explore the respective role of these ILC1 subsets in human celiac disease or mouse models of celiac disease." (PMID 24982658, 2014). "In isolation, our IL-15 and ALDH1A2 data would argue against the potential for hookworm infection to protect against gluten toxicity in celiac disease, the primary incentive for undertaking this clinical trial." (PMID 22346753, 2012). "The autoimmune upregulation of LAT in celiac disease may be driven by chronic signaling through stress receptors such as NKG2D and CD94, as well as IL-15 that is highly expressed in active disease." (PMID 40463269, 2025). "For example, freshly isolated CD8+ TCRαβ+ intraepithelial lymphocytes (IELs) from patients with active celiac disease or IELs prestimulated with IL-15 exhibit NKG2D-mediated cytotoxicity without TCR engagement." (PMID 31827070, 2019).
celiac disease (continued). "For IL‐15 antagonism, active development is underway in related immune conditions, including ordesekimab/PRV‐015 in non‐responsive coeliac disease (NCT04424927; prior AMG‐714 study NCT02637141) and CALY‐002 in coeliac disease/eosinophilic oesophagitis (NCT04593251)." (PMID 41039829, 2025). "IL‐15 may be released from epithelium upon its stimulation by gliadin (Valérie & Bana, 2014) and plays a critical role in IEL‐mediated epithelial cell damage and in dysregulated immune responses during celiac disease." (PMID 34125490, 2021). "It is interesting to note that interleukin-15 (IL15), but not IL8, can induce the transcription of NEAT1 by recruiting the signal transducer and activator of transcription 3 (STAT3) to its promoter in celiac disease (CD) patients." (PMID 40362651, 2025).